OGG1 (8-oxoguanine DNA glycosylase)
Description:
DNA repair enzyme that incises DNA at 8-oxoG residues. Excises 7,8-dihydro-8-oxoguanine and 2,6-diamino-4-hydroxy-5-N-methylformamidopyrimidine (FAPY) from damaged DNA. Has a beta-lyase activity that nicks DNA 3' to the lesion.
Synonyms: MUTM; OGH1; HMMH; HOGG1
Tractability: Small molecule: a structure with a bound ligand is known; a high-quality ligand is known. PROTAC: ubiquitination databases record sites on it; a small molecule that binds it is known.
Target class: Enzyme
Gene: Protein-coding gene on chromosome 3 (9,749,944 to 9,788,219, forward strand). Ensembl gene ENSG00000114026.
Subcellular location: Nucleus, nucleoplasm; Nucleus speckle; Nucleus matrix; Nucleus (Isoform 1A); Mitochondrion (Isoform 2A)
Subcellular location (Human Protein Atlas): Nucleoplasm
Pathways (Reactome):
DNA Repair: APEX1-Independent Resolution of AP Sites via the Single Nucleotide Replacement Pathway; Cleavage of the damaged purine; Cleavage of the damaged pyrimidine; Displacement of DNA glycosylase by APEX1; Recognition and association of DNA glycosylase with site containing an affected purine; Recognition and association of DNA glycosylase with site containing an affected pyrimidine
Disease: Defective OGG1 Localization; Defective OGG1 Substrate Binding; Defective OGG1 Substrate Processing
Gene Ontology:
Molecular function: 8-oxo-7,8-dihydroguanine DNA N-glycosylase activity; damaged DNA binding; DNA binding; enzyme binding; oxidized purine DNA binding; protein binding; RNA polymerase II cis-regulatory region sequence-specific DNA binding; endonuclease activity; oxidized purine nucleobase lesion DNA N-glycosylase activity; catalytic activity; class I DNA-(apurinic or apyrimidinic site) endonuclease activity; microtubule binding
Biological process: cellular response to reactive oxygen species; DNA damage response; negative regulation of double-strand break repair via single-strand annealing; nucleotide-excision repair; positive regulation of gene expression via chromosomal CpG island demethylation; positive regulation of transcription by RNA polymerase II; regulation of DNA-templated transcription; response to oxidative stress; response to radiation; base-excision repair; base-excision repair, AP site formation; depurination; depyrimidination; DNA repair
Cellular component: mitochondrion; nuclear matrix; nuclear speck; nucleoplasm; nucleus; protein-containing complex; cytosol; mitochondrial matrix
Genetic constraint (gnomAD): Loss-of-function variants: 39 observed, 46.35 expected, observed/expected ratio (o/e) 0.84, 90% interval 0.65 to 1.1. The upper end of that interval is the gene's LOEUF score, 1.1, which puts it in group 4 of 6, group 1 being the genes least tolerant of losing a copy. Missense variants: 484 observed, 467.83 expected, observed/expected ratio (o/e) 1.03, 90% interval 0.96 to 1.12. Synonymous variants: 189 observed, 188.03 expected, observed/expected ratio (o/e) 1.01, 90% interval 0.89 to 1.13.
Homologues: Orthologues: chimpanzee OGG1 (94% identical), macaque OGG1 (89% identical), mouse Ogg1 (85% identical), dog OGG1 (82% identical), rat Ogg1 (79% identical), guinea pig OGG1 (73% identical), tropical clawed frog ogg1 (52% identical), zebrafish ogg1 (52% identical), Drosophila melanogaster Ogg1 (34% identical).
Diseases named in the same sentence as OGG1 in open-access papers:
OGG1 is named in the same sentence as 250 diseases in open-access papers, as found by Europe PMC text mining. Sharing a sentence is not in itself a finding about the gene and the disease. The quoted sentences say what the papers report.
lung carcinoma (63 papers, 2002 to 2025). "It was shown that high AAG enzyme activity is associated with lung cancer risk, which is opposite to the effect of OGG1." (PMID 40806775, 2025). "It has been also reported that a personal low baseline DNA repair score, composed of the BER-associated enzymatic activities of APEX1, MPG and OGG1 (all of which act primarily on oxidative DNA damage) consists of a strong risk factor for lung cancer." (PMID 35740268, 2022). "Specifically, S326C is a frequently occurring mutation in OGG1 that has been associated with various cancers such as lung cancer, prostate cancer, and breast cancer." (PMID 33203705, 2021). "In agreement, reduced activity and functional polymorphisms of OGG1 are associated with various types of human cancer, including lung cancer, and mutations in the MUTYH gene confer a heritable form of colorectal cancer predisposition." (PMID 32547565, 2020). "The corresponding authors (ZL and TPE) have an issued patent on the OGG1 risk factor for lung cancer and patent applications issued and pending for the OGG1, MPG, and APE1 panel of DNA Repair biomarkers." (PMID 32064457, 2020). "We therefore examined the utility for lung cancer risk assessment of a DNA Repair score obtained from OGG1, MPG, and APE1 blood tests." (PMID 32064457, 2020). "A previous study on lung cancer patients showed a close relationship between Ser326Cys polymorphism and OGG1 mRNA levels." (PMID 28415770, 2017). "AKR1C3 and OGG1 genotypes were significantly associated with higher risk of lung cancer, especially among heavily exposed women." (PMID 25603868, 2015). "The GSTM1-null genotype, the AKR1C3 (Ex1-70C > G), OGG1 (Ex6-315C > G) genotypes were closely associated with increased risk of lung cancer in Xuanwei County, and their odds ratios (95%CI) were 2.3 (1.3-4.2), 1.8 (1.0-3.5) and 1.9 (1.1-3.3), respectively." (PMID 25603868, 2015). "Of these enzymes, only 8-oxoguanine DNA glycosylase (OGG1) has been implicated in the development of lung cancer and cancers from other organs." (PMID 24595271, 2014). "Epidemiological studies of the OGG1 Ser326Cys polymorphism in relation to cancer have yielded mixed results with a weak association between the OGG1 Ser326Cys genotype and the risk of lung cancer." (PMID 23971971, 2013). "Because the results from these studies were inconsistent, we performed a meta-analysis of the published reports to further evaluate the association of OGG1 Ser326Cys SNPs with the risk of lung cancer." (PMID 22540013, 2012). "Numerous studies have investigated association of OGG1 Ser326Cys polymorphism with lung cancer susceptibility; however, the findings are inconsistent." (PMID 22540013, 2012). "We searched publications from MEDLINE and EMBASE which were assessing the associations between OGG1 Ser326Cys polymorphism and lung cancer risk." (PMID 22540013, 2012). "Meta-analysis of the association between OGG1 Ser326Cys polymorphism and lung cancer with definite histological types." (PMID 22540013, 2012). "In our current study, we elucidate the association between plasma levels of 8-OHdG and the OGG1 repair capacity among lung cancer cases and controls." (PMID 20718982, 2010). "It has also been reported that lower enzymatic levels of OGG1 in peripheral lymphocytes correlated with an increased risk of lung cancer among smokers." (PMID 20718982, 2010). "The authors reported that the OGG1 activity was significantly decreased in lung cancer cases, and that the risk of developing lung cancer in smokers with low OGG1 activity was significantly higher compared to smokers with high OGG1 activity." (PMID 20718982, 2010). "In this study, we tried to assess reported studies of association between polymorphism of human 8-oxoguanine DNA glycosylase 1 (hOGG1) Ser326Cys and lung cancer." (PMID 24281202, 2010).
lung carcinoma (continued). "In some patient-control studies, OGG1 Ser326Cys appeared to be associated with an increased risk for lung cancer, whereas the findings of this association study have been inconsistent." (PMID 19161591, 2009). "It has been reported that the OGG1 Cys allele in Japanese patients is associated with an increased risk for lung cancer." (PMID 19161591, 2009). "Previous reports showed that loss of hetrozygosity (LOH) of 3p, which includes OGG1 gene, was very common in lung cancer tissues)." (PMID 12164330, 2002). "The association between OGG1 Ser326Cys polymorphism and the risk of lung cancer has been investigated in 3 studies)." (PMID 12164330, 2002). "In addition, the OGG1 rs1052133 CC genotype (OR = 2.588, 95%CI: 1.035‐6.474) exhibited a higher risk of lung cancer development in females." (PMID 30453383, 2018). "OGG1 is a key enzyme of BER to identify and excise 8‐oxoG lesions that induced transversions from G:C to T:A.35, 36, 37 Similarly, Liu et al14 observed that C allele site of OGG1 rs1052133, jointed effects with a smoking habit, exerted an adverse influence on lung cancer risk in Asia." (PMID 30453383, 2018). "Mutations and single nucleotide polymorphisms (SNPs) in BER genes are associated with numerous cancers, such as UNG2 (uracil DNA glycosylase) mutations in glioblastoma, MED1 (mediator complex subunit 1) mutations in colorectal cancer, and OGG1 (8-oxoguanine DNA glycosylase) mutations in lung cancer." (PMID 26967246, 2016). "More importantly, the homozygous variant genotype OGG1 326Cys has been shown associated with increased risk for many different types of cancers, including colorectal cancer, hepatocellular carcinoma and lung cancer." (PMID 24893568, 2014). "Meta-analysis of the association between OGG1 Ser326Cys polymorphism and lung cancer risk." (PMID 22540013, 2012). "However, further studies are warranted to validate the association between the OGG1 Ser326Cys polymorphism and lung cancer risk with larger sample size and more detailed histological types." (PMID 22540013, 2012). "For OGG1, there are twenty five SNPs that reportedly change amino acid of the protein but only Ser326Cys (rs1052133) was extensively investigated for its association with cancer risk, in particular for lung cancer." (PMID 22540013, 2012). "In a previous meta-analysis with 17 studies consist of 6375 cases and 6406 controls, significantly increased risks were found among Asian subjects in a dominant model, and lung cancer risk associated with the OGG1 Cys/Cys genotype was significantly increased in population-based studies." (PMID 22540013, 2012). "Relevant studies were identified through a search of MEDLINE, PubMed, Web of Science, EMBASE, and Chinese Biomedical Literature database (CBM) using terms “lung cancer”, “hOGG1” or “OGG1”, “polymorphism” or “variation” and the last search updated on May 1, 2013." (PMID 23971971, 2013). "Although increased expression levels of OGG1 might be considered beneficial to the cells, it should be emphasized that in human beings, with the variant form of OGG1 (Ser326Cys) genotype, high expression levels of OGG1 mRNA in leukocytes is associated with increased risk of lung cancer." (PMID 19479010, 2009). "Our previous research has demonstrated that OGG1 is crucial for the proliferation and metastasis of lung cancer cells under oxidative stress." (PMID 40227353, 2025). "Recently, we highlighted chief aspects of OGG1 involvement in regulation of gene expression, which hold significance in lung cancer development." (PMID 38201575, 2023). "Researchers found an abnormal increase in 8-oxoG accumulation and a high spontaneous rate of lung cancer in the genome of Ogg1-/-mice." (PMID 35624797, 2022). "Case-control studies carried out in populations of different diseases, regions or life states, together with meta-analysis based on them, tried to figure out the correlation between OGG1 and lung cancers, and the conclusions were inconsistent." (PMID 35624797, 2022).
lung carcinoma (continued). "Larger puff volume was also associated with increased differential expression of 8-oxoguanine glycosylase 1 (OGG1; a lung cancer) gene in buccal and blood samples." (PMID 33809907, 2021). "To examine whether a low DNA Repair score is associated with lung cancer risk in the United Kingdom, we conducted a case-control study with 150 non–small cell lung cancer case patients and 143 control individuals for whom we tested the enzymatic activities for OGG1, MPG, and APE1 in PBMC." (PMID 32064457, 2020). "Surprisingly, Ogg1−/− mice are alive and grow old, albeit having increased incidence of lung cancer at the age of 18 months." (PMID 33211885, 2020). "In human cancer cell lines, depletion of OGG1 in H460 lung cancer cells stably transfected with doxycycline-inducible small hairpin RNA (shRNA) constructs targeting OGG1 reduced clonogenic ability." (PMID 33211885, 2020). "The genetic polymorphisms (rs2853669 in TERT, rs1052133 in OGG1, and rs16969968 in CHRNA5 genes) were shown to be strongly associated with the risk of lung cancer." (PMID 32257438, 2020). "The results presented here indicate that a personal low baseline DNA Repair score, composed of the enzymatic activities of OGG1, MPG, and APE1, is a strong risk factor for lung cancer." (PMID 32064457, 2020). "This was associated with a several-fold increased accumulation of genomic 8-oxo-dG, which is consistent with the chromosome 3p25 location of the human OGG1 gene, a locus frequently lost in lung cancer." (PMID 25029543, 2014). "In summary, results from this study suggest that high levels of 8-OHdG are correlated with high levels of oxidative DNA residual damage and suboptimal OGG1 repair capacity all of which were predominantly seen in the lung cancer case group." (PMID 20718982, 2010). "We analyzed associations among OGG1 Ser326Cys and MUTYH Gln324His gene polymorphisms in relation to lung cancer risk using PCR-RFLP." (PMID 19161591, 2009). "Herein, we report that gene polymorphisms, OGG1 Ser326Cys and MUTYH Gln324His, of two DNA repair genes in the BER pathway can modulate lung cancer risk in a small case-control study." (PMID 19161591, 2009). "Next, to explore whether OGG1 is involved in lung cancer metastasis under oxidative stress, we first conducted OGG1 loss‐of‐function experiments with small interfering RNA (siRNA)." (PMID 39235072, 2024). "Lung cancer: In advanced inoperable non-small cell lung cancer (NSCLC) patients who received treatment with platinum-based chemotherapy, the OGG1 genetic allele variant carrying a C-to-G substitution at codon 326 was associated with poor progression-free survival." (PMID 38201575, 2023). "Interestingly, there have been studies over the role of OGG1 in lung cancer separated into different directions at the very beginning." (PMID 35624797, 2022). "Some researchers summarized that OGG1 has no relation to a higher risk of lung cancer, or if the association appeared in certain populations, such as in non-smokers." (PMID 35624797, 2022). "The human OGG1 gene is located on chromosome 3p25, a locus frequently lost in lung cancer." (PMID 25029543, 2014). "We conducted a meta-analysis of published studies to evaluate the association between the OGG1 Ser326Cys polymorphism and lung cancer risk because no such up-to-date meta-analysis including histological types has been published to date." (PMID 22540013, 2012). "The effect of tobacco exposure and the OGG1 Ser326Cys showed also no significant risk for lung cancer." (PMID 19161591, 2009).
lung carcinoma (continued). "In this study, we assessed the OGG1 Ser326Cys, MUTYH Gln324His, APEX1 Asp148Glu, XRCC1 Arg399Gln, and XRCC3 Thr241Met gene polymorphisms that may influence DNA repair capacity and their association with the overall survival of lung cancer patients." (PMID 23443124, 2012). "In conclusion, our study shows that the Comet/FLARE assay is a relatively rapid and useful method for determination of DNA repair capacity and that adduct removal by OGG1 is a mechanism that might be significantly impaired among smokers who develop lung cancer." (PMID 20718982, 2010). "Furthermore, we hypothesized that lung cancer patients have higher levels of 8-OHdG reflecting suboptimal OGG1 repair capacity when compared to healthy controls." (PMID 20718982, 2010). "Therefore, we specifically examined whether two gene polymorphisms, OGG1 Ser326Cys and MUTYH Gln324His play an interactive role in the risk for lung cancer incidence in relation to the histological subtypes and the smoking status." (PMID 19161591, 2009). "However, the OGG1 Ser/Cys or Cys/Cys genotypes compared with the Ser/Ser genotype did not have significantly increased risk for lung cancer, containing either adenocarcinoma or squamous cell carcinoma." (PMID 19161591, 2009). "In summary, inhibitors of CDK4/6 sensitize lung cancer cells to oxidative stress-inducing anticancer drugs by creating a functional link between RB1, PARP1, and OGG1." (PMID 29306194, 2018). "The influence of AAG and OGG1 activity on the development of lung cancer in smoking and non-smoking patients was investigated." (PMID 40806775, 2025). "Human 8-oxoguanine DNA glycosylase (hOGG1) is relative to DNA oxidative damage and repair, and flap structure-specific endonuclease 1 (FEN1) plays a crucial role in DNA replication and cell proliferation, both of which are promising biomarkers in lung cancer." (PMID 38188023, 2023). "Early on, it was demonstrated that lung cancer development in Ogg1−/− mice, lacking the 8‐oxoguanine glycosylase OGG1, was dependent on a functional MTH1 protein, as Ogg1−/− Mth1−/− double knockout mice were spared from cancer." (PMID 35583750, 2022). "In this study, seven candidate SNPs in 3′UTR of DRC‐related genes including ERCC1 (rs3212986, rs2336219, and rs735482), OGG1 (rs1052133), MLH3 (rs108621), CD3EAP (rs1007616), and PPP1R13L (rs6966) were analyzed in 300 lung cancer patients and controls from the northeast of China." (PMID 30453383, 2018). "We focused on OGG1 Ser326Cys, MUTYH Gln324His, APEX1 Asp148Glu, XRCC1 Arg399Gln, and XRCC3 Thr241Met and examined the relationship between the different genotypes and survival of Japanese lung cancer patients." (PMID 23443124, 2012). "Our results indicated that lung cancer risk was found to be 3-fold in individuals with the homozygous His/His genotype of MUTYH Gln324His (95%CI 1.31–7.00, p = 0.010), whereas that was not with that of OGG1 Ser326Cys." (PMID 19161591, 2009). "However, there have been no previous reports on OGG1, MUTYH, and APEX1 with regard to survival in lung cancer." (PMID 23443124, 2012).